DNM1 (dynamin 1)
Description:
Catalyzes the hydrolysis of GTP and utilizes this energy to mediate vesicle scission and participates in many forms of endocytosis, such as clathrin-mediated endocytosis or synaptic vesicle endocytosis as well as rapid endocytosis (RE). Associates to the membrane, through lipid binding, and self-assembles into rings and stacks of interconnected rings through oligomerization to form a helical polymer around the vesicle membrane leading to constriction of invaginated coated pits around their necks. Self-assembly of the helical polymer induces membrane tubules narrowing until the polymer reaches a length sufficient to trigger GTP hydrolysis. Depending on the curvature imposed on the tubules, membrane detachment from the helical polymer upon GTP hydrolysis can cause spontaneous hemifission followed by complete fission. May play a role in regulating early stages of clathrin-mediated endocytosis in non-neuronal cells through its activation by dephosphorylation via the signaling downstream of EGFR. Controls vesicle size at a step before fission, during formation of membrane pits, at hippocampal synapses (By similarity). Controls plastic adaptation of the synaptic vesicle recycling machinery to high levels of activity (By similarity). Mediates rapid endocytosis (RE), a Ca(2+)-dependent and clathrin- and K(+)-independent process in chromaffin cells (By similarity). Microtubule-associated force-producing protein involved in producing microtubule bundles and able to bind and hydrolyze GTP (By similarity). Through its interaction with DNAJC6, acts during the early steps of clathrin-coated vesicle (CCV) formation.
Synonyms: DNM; DEE31; DEE31A; DEE31B; EIEE31
Tractability: Small molecule: a structure with a bound ligand is known; a high-quality ligand is known; it has a high-quality binding pocket. Antibody: UniProt places it where antibodies can reach, with high confidence; its Gene Ontology location is reachable by antibodies, with high confidence. PROTAC: ubiquitination databases record sites on it; its protein half-life has been measured; a small molecule that binds it is known.
Target class: Structural protein
Gene: Protein-coding gene on chromosome 9 (128,191,655 to 128,255,248, forward strand). Ensembl gene ENSG00000106976.
Subcellular location: Cell membrane; Membrane, clathrin-coated pit; Cytoplasmic vesicle; Presynapse; Cytoplasmic vesicle, secretory vesicle, chromaffin granule
Pathways (Reactome):
Vesicle-mediated transport: Clathrin-mediated endocytosis; Formation of annular gap junctions; Gap junction degradation
Developmental Biology: EPH-ephrin mediated repulsion of cells; Recycling pathway of L1
Immune System: MHC class II antigen presentation; Toll Like Receptor 4 (TLR4) Cascade
Signal Transduction: Retrograde neurotrophin signalling
Gene Ontology:
Molecular function: GTPase activity; identical protein binding; phosphatidylinositol-3,4,5-trisphosphate binding; phosphatidylinositol-4,5-bisphosphate binding; protein binding; protein homodimerization activity; RNA binding; GDP binding; microtubule binding; protein kinase binding; GTP binding
Biological process: endocytosis; endosome organization; protein homooligomerization; protein homotetramerization; receptor-mediated endocytosis; vesicle scission; clathrin coat assembly involved in endocytosis; regulation of vesicle size; synaptic vesicle budding from presynaptic endocytic zone membrane
Cellular component: clathrin-coated pit; extracellular exosome; plasma membrane; cytoplasmic vesicle; endocytic vesicle; presynapse; synapse; chromaffin granule; membrane
Genetic constraint (gnomAD): Loss-of-function variants: 26 observed, 86.41 expected, observed/expected ratio (o/e) 0.3, 90% interval 0.22 to 0.42. The upper end of that interval is the gene's LOEUF score, 0.42, which puts it in group 1 of 6, group 1 being the genes least tolerant of losing a copy. Missense variants: 615 observed, 1,064.5 expected, observed/expected ratio (o/e) 0.58, 90% interval 0.54 to 0.62. Synonymous variants: 421 observed, 422.54 expected, observed/expected ratio (o/e) 1, 90% interval 0.92 to 1.08.
Gene-disease validity (ClinGen):
ClinGen rates the evidence that DNM1 causes each of these diseases.
genetic developmental and epileptic encephalopathy (autosomal dominant): Definitive. A complex neurodevelopmental disorder characterized by a range of developmental delays and epileptic encephalopathy phenotypes.
genetic developmental and epileptic encephalopathy (autosomal recessive): Moderate.
Homologues: Orthologues: macaque DNM1 (100% identical), guinea pig DNM1 (98% identical), mouse Dnm1 (98% identical), dog DNM1 (98% identical), rat Dnm1 (97% identical), chimpanzee DNM1 (95% identical), pig DNM1 (93% identical), tropical clawed frog dnm1 (92% identical), zebrafish dnm1a (88% identical), zebrafish dnm1b (88% identical), rabbit DNM1 (52% identical). Paralogues in human: DNM3 (80% identical), DNM2 (79% identical), DNM1L (35% identical), MX1 (22% identical), MX2 (22% identical), OPA1 (19% identical).
Diseases named in the same sentence as DNM1 in open-access papers:
DNM1 is named in the same sentence as 87 diseases in open-access papers, as found by Europe PMC text mining. Sharing a sentence is not in itself a finding about the gene and the disease. The quoted sentences say what the papers report.
epilepsy (27 papers, 2010 to 2025). A brain disorder characterized by episodes of abnormally increased neuronal discharge resulting in transient episodes of sensory or motor neurological dysfunction, or psychic dysfunction. "Epilepsy is generally intractable in patients carrying DNM1 variants, and the efficacy of antiepileptic drugs is limited." (PMID 38903324, 2024). "In summary, we reported a novel non-sense variant in the DNM1 leading to severe neurodevelopmental phenotype in the patient that includes early-onset epilepsy, hypotonia, intellectual disability, seizures episodes, and pronounced developmental delay." (PMID 37900685, 2023). "Clinically, affected individuals having DNM1 heterozygous missense variants show phenotypic heterogeneity with early-onset epilepsy, hypotonia, and developmental delay." (PMID 37900685, 2023). "In conclusion, we provide further evidence that deleterious homozygous loss-of-function variants in DNM1 can lead to severe neurodevelopmental defects characterized by epilepsy, global developmental delay, and hypotonia." (PMID 36553519, 2022). "DNM1 encephalopathy in humans is a neurological disorder that causes severe epilepsy with mutations in the gene DNM1 (dynamin 1)." (PMID 32844156, 2020). "Given that DNM1 mutations are present in up to 2% of patients with severe epilepsy, this mutation is particularly frequent in patients with epileptic encephalopathy." (PMID 31920647, 2019). "For two patients, evidence of developmental delay was noted before the onset of epilepsy suggesting an effect of DNM1 variants on neurodevelopment unrelated to seizure activity." (PMID 26125563, 2015). "Previous studies have extensively examined the function and mechanisms of action of Dnm1, but this study is the first to identify a Dnm1 mutation that leads to epilepsy." (PMID 20700442, 2010). "Various seizure types may be present, including focal seizures, generalized tonic-clonic seizures, and myoclonic seizures, reflecting the broad spectrum of epilepsy phenotypes associated with DNM1 variants." (PMID 39596051, 2024). "Prior to the association of pathogenic human variants in DNM1 and severe epilepsy, a spontaneous missense mutation in the mouse ortholog, called “fitful,” had already been associated with epilepsy, and fitful homozygotes exhibit a DEE-like phenotype with developmental delay and severe seizures." (PMID 35250833, 2022). "This hypothesis is supported by the fact that mutations in Dlg3, Psen1, Dnm1, and Ppp3ca have been found in epilepsy patients." (PMID 32033586, 2020). "Finally, isoform switching in the mouse gene Dnm1 (encoding dynamin-1), as a result of alternative splicing of exon 10 during embryonic to postnatal development, causes epilepsy." (PMID 28558813, 2017). "Given that DNM1 mutations account for up to 2% of patients with severe epilepsy, this mutation may represent one of the most frequent single mutations in patients with epileptic encephalopathies." (PMID 28667181, 2017). "Notably, a wide range of clinical phenotypes, ranging from ASD, cognitive impairment, and various types of epilepsy and seizures, have been related to de novo heterozygous missense or nonsense DNM1 pathogenic variants, probably resulting in a disrupted protein." (PMID 39596051, 2024). "Mutations in dynamin 1 have been observed to cause epileptic symptoms, while in both animal models and human epilepsy dynamin 1 is upregulated and may contribute to the development of seizures, with dynamin inhibition, by the small molecule inhibitor Dynasore, exhibiting anti-epileptic effects." (PMID 35115907, 2021).
epilepsy (continued). "Other investigators found that the dynamin 1 expression pattern was altered in the pilocarpine rat model of epilepsy and patients with temporal lobe epilepsy." (PMID 38776036, 2024). "We find that patients with DNM1 encephalopathy have a relatively homogeneous phenotype of severe to profound intellectual disability, hypotonia, and epilepsy starting with infantile spasms with frequent evolution to Lennox-Gastaut syndrome." (PMID 28667181, 2017). "In the same way, several DEEs caused by mutations in CDKL5, DNM1, KCNT1, SCN1A, SCN2A, SCN8A, and UBA5 genes, which present severe pharmaco-resistant epilepsy, are increasingly becoming targets for RNA molecules that aim to restore neuronal excitability and network function." (PMID 41244709, 2025). "We hypothesize that the upregulation of NMDAR interactors, such as Dlg3, Myh10, Ppp3a, Psen1, and Dnm1, may contribute to the anti-epilepsy phenotype by keeping the activity of NMDARs in control." (PMID 32033586, 2020). "Altered expression of DNM1 has been detected in AD, epilepsy and schizophrenia." (PMID 32807865, 2020). "Here, we report the first documented DNM1 variant in the PH domain associated with a milder phenotype without epilepsy." (PMID 29397573, 2018). "However, we have reason to believe that the phenotypic spectrum with prominent epilepsy presented in our study reflects the overall clinical picture of DNM1 encephalopathy." (PMID 28667181, 2017). "Wildtype Dnm1 deletion from Dnm1Ftfl inhibitory neurons is sufficient to cause early onset epilepsy and premature death, without other obvious behavioral impairment." (PMID 26125563, 2015). "This suggests a graded seizure onset and lethality corresponding to the extent of Dnm1 depletion and also points to network-specific effects that may contribute to decreased inhibition and the seizure disorder." (PMID 26125563, 2015). "Wildtype Dnm1 deletion from the majority of Dnm1Ftfl inhibitory neurons is sufficient to cause early onset epilepsy and premature death, without other obvious behavioral impairment." (PMID 26125563, 2015). "The three affected siblings lacked epilepsy and showed symptoms of ADHD, although DNM1 has not yet been associated with ADHD." (PMID 37805537, 2023). "The dysregulated Dnm1, Actb, and Prnp interact with Grin1, suggesting that NMDAR system (NMDARs and their regulators) might contribute to the anti-epilepsy phenotype of this mouse model." (PMID 32033586, 2020).
Epileptic encephalopathy (21 papers, 2015 to 2025). A condition in which epileptiform abnormalities are believed to contribute to the progressive disturbance in cerebral function. "DNM1 variants have been linked not only to developmental and epileptic encephalopathies or synaptic vesicle cycling disorders, but also to the LSS, as reported by several authors." (PMID 40717768, 2025). "Dynamin 1 (DNM1) is a guanosine triphosphatase engaged in clathrin-mediated endocytosis, and de novo mutations in synaptic transmission genes including DNM1 were reported to be a causative factor in epileptic encephalopathies." (PMID 38776036, 2024). "Heterozygous variants in DNM1 are associated with epileptic encephalopathy, such as infantile epileptic spasms syndrome and Lennox-Gastaut syndrome." (PMID 38903324, 2024). "Pathogenic DNM1 variants affect brain development and function and cause epileptic encephalopathy with severe neurodevelopmental complications." (PMID 38903324, 2024). "All missense variants associated with epileptic encephalopathy cluster in the two major functional domains of the DNM1 protein, the GTPase domain, and the middle domain." (PMID 37900685, 2023). "To date, 46 patients with epileptic encephalopathy and DNM1 pathogenic variants have been described in 45 families." (PMID 37900685, 2023). "Previously, only de novo variants in the DNM1 were linked to developmental and epileptic encephalopathy (MIM 620352, MIM 616346)." (PMID 37900685, 2023). "Heterozygous missense mutations in the dynamin-1 gene (DNM1) cause a novel form of epileptic encephalopathy, with pathogenic mutations clustering within regions required for its essential GTPase activity." (PMID 37648685, 2023). "Among these, deleterious variants in the DNM1 gene have been responsible for diverse neurodevelopmental phenotypes and cerebral dysfunctions such as early-onset epileptic encephalopathies." (PMID 37900685, 2023). "For example, mutations in DYNAMIN1 (DNM1) cause epileptic encephalopathy, whereas DYNAMIN2 (DNM2) is found mutated in microcytic anemia, centronuclear myopathy, and Charcot-Marie-Tooth disease." (PMID 37060997, 2023). "Considering the essential role for dynamin-1 in SV endocytosis and the clustering of mutations within the GTPase domain in individuals with epileptic encephalopathy, a logical prediction is that defects in SV endocytosis underpin this disorder." (PMID 37648685, 2023). "Pathogenic DNM1 variants affect brain development and function and cause epileptic encephalopathy associated with global DD." (PMID 37805537, 2023). "As another example, while DNM1 loss of function can result in developmental and epileptic encephalopathies, specific SDVs yield in-frame insertions which act in a dominant negative fashion and cause a particularly severe presentation." (PMID 38129864, 2023). "Heterozygous pathogenic variants in DNM1 are linked to an autosomal dominant form of epileptic encephalopathy." (PMID 36553519, 2022). "Rare variants in DNM1 have been identified in patients with a mendelian phenotype, epileptic encephalopathy, and in some cases of intellectual disability with seizures." (PMID 35013130, 2022). "Recently, homozygous loss-of-function variants in DNM1 were reported to cause an autosomal recessive form of developmental and epileptic encephalopathy in unrelated patients." (PMID 36553519, 2022). "shi encodes a dynamin and one of its human orthologs, DNM1, is linked to an early infantile epileptic encephalopathy (OMIM #616346)." (PMID 33659928, 2021). "The clinical features of 33 cases with pathogenic DNM1 variants were analyzed and the results showed that patients carrying pathogenic variants in the GTPase or middle domains present with epileptic encephalopathy and severe neurodevelopmental symptoms." (PMID 31920647, 2019). "Epileptic encephalopathy, caused by dynamin-1 (DNM1) mutations, is a newly characterized neurologic disorder in children." (PMID 31920647, 2019).
Epileptic encephalopathy (continued). "Previously reported pathogenic variants of DNM1 have been associated with early onset of epileptic encephalopathy (including West and Lennox-Gastaut syndromes) and are present in up to 2% of patients with infantile spasms or Lennox-Gastaut syndrome." (PMID 31920647, 2019). "Epileptic encephalopathy, caused by mutations in the dynamin-1 (DNM1; NM_004408) gene, is a newly identified neurologic disorder in children." (PMID 31920647, 2019). "Here, we characterized the phenotypic, genetic, and electroencephalographic features of children with DNM1 mutation-related epileptic encephalopathy." (PMID 31920647, 2019). "EEG results were abnormal in 30 out of 31 (96.7%) patients with DNM1 mutation-related epileptic encephalopathy." (PMID 31920647, 2019). "Pathogenic DNM1 variants affect brain development and function and cause epileptic encephalopathy associated with severe neurodevelopmental complications." (PMID 31920647, 2019). "The aim of this study is to characterize the phenotypic, genetic, and electroencephalographic features of children with DNM1 mutation-related epileptic encephalopathy." (PMID 31920647, 2019). "From the 31 patients with DNM1 mutation-related epileptic encephalopathy, 29 (93.5%) experienced epileptic seizures." (PMID 31920647, 2019). "The long-term outcomes of patients with DNM1 mutation-related epileptic encephalopathy were often disappointing." (PMID 31920647, 2019). "For many years, considerable attention has been paid to the genetic studies, patients carrying pathogenic variants in the GTPase or middle domains of DNM1 exhibit epileptic encephalopathy and severe neurodevelopmental complications." (PMID 31920647, 2019). "In this study of epileptic encephalopathies in 31 patients carrying DNM1 mutations, approximately 96.7% of patients' recordings portrayed abnormal EEG; multifocal discharge was most common (58.1%), followed by hypsarrhythmia (45.2%)." (PMID 31920647, 2019). "EEG is an important tool for assessment of the diagnosis and prognosis of epileptic encephalopathy in patients carrying DNM1 mutations." (PMID 31920647, 2019). "Pathogenic variants in DNM1 have been implicated in global developmental delay (DD), severe intellectual disability (ID), and notably, epileptic encephalopathy." (PMID 29397573, 2018). "This includes the gene DNM1; a gene that was recently observed in five individuals with epileptic encephalopathy to harbor de novo mutations." (PMID 26403471, 2015). "Variants of dynamin 1 (DNM1) are typically linked to synaptic disorders, which may lead to developmental and epileptic encephalopathies." (PMID 40608007, 2025). "Similarly, while DNM1 loss of function can result in developmental and epileptic encephalopathies, specific SDVs yield in-frame insertions which act in a dominant negative fashion and cause a particularly severe presentation." (PMID 37205456, 2023). "In addition, homozygous loss-of-function pathogenic variants in DNM1 have been reported to cause a severe autosomal recessive developmental and epileptic encephalopathy in three unrelated patients." (PMID 37900685, 2023). "Therefore, reports of additional patients are needed to define the relationship between genotype and phenotype in DNM1 mutation-related epileptic encephalopathy." (PMID 31920647, 2019). "Thus far, there are no international guidelines for the pharmacological treatment of DNM1 mutation-related epileptic encephalopathy because of the limited efficacy of antiepileptic medications." (PMID 31920647, 2019). "Although all previously reported patients with DNM1 pathogenic variants exhibited epileptic encephalopathy and severe neurological phenotype, the two probands in this report had no seizures and exhibited mild to moderate DD/intellectual disability (ID) and autism spectrum disorder." (PMID 29397573, 2018).